RAB8A (RAB8A, member RAS oncogene family)
Diseases named in the same sentence as RAB8A in open-access papers:
RAB8A is named in the same sentence as 62 diseases in open-access papers, as found by Europe PMC text mining. Sharing a sentence is not in itself a finding about the gene and the disease. The quoted sentences say what the papers report.
Parkinson disease (12 papers, 2016 to 2025). A progressive degenerative disorder of the central nervous system characterized by loss of dopamine producing neurons in the substantia nigra and the presence of Lewy bodies in the substantia nigra and locus coeruleus. "Mutations in Leucine rich repeat kinase 2 (LRRK2) that is a major regulator of both idiopathic and genetic forms of Parkinson’s Disease (PD) cause hyperactivation of its kinase activity and are implicated in phosphorylation of Rab8a, Rab10 and Rab12 in cultured human and mouse cells, and mice." (PMID 40395934, 2025). "The most common cause of familial Parkinson’s disease is linked to mutations in the leucine rich-repeat kinase 2 (LRRK2) protein that phosphorylates Rab10, Rab8a, Rab12 and Rab35." (PMID 40801573, 2025). "Rab8a is one of several Rab GTPases that are substrates of leucine-rich repeat kinase 2 (LRRK2), a serine/threonine kinase that is linked to Parkinson's disease." (PMID 32017888, 2020). "Parkinson’s disease-associated LRRK2 kinase phosphorylates multiple Rab GTPases, including Rab8A and Rab10." (PMID 30398148, 2018). "Moreover, overexpression of Rab8a, Rab1 and Rab3a protein attenuated α-synuclein-induced cytotoxicity in cellular and animal models of Parkinson's disease." (PMID 27474410, 2016). "Finally, another protein kinase mutated in Parkinson's disease termed PINK1, indirectly controls the phosphorylation of a small group of Rabs including Rab8A at a site distinct from that used by LRRK2 (Ser111 on Rab8A)." (PMID 27474410, 2016).
ciliopathy (9 papers, 2012 to 2025). A genetic disorder of the cellular cilia or the cilia anchoring structures, the basal bodies, or of ciliary function. "From these observations, and the absence of cysts in the kidney and retinal degeneration, both of which are hallmarks of some ciliopathies, we concluded that Rab8a and Rab8b are not sufficient for the formation of cilia, at least during the lifespan of the DKO mice." (PMID 24213529, 2014).
endometrial cancer (5 papers, 2014 to 2025). Primary or metastatic malignant neoplasm involving the endometrium (mucous membrane that lines the endometrial cavity). "RAB8A itself has been shown to be associated with endometrial cancer." (PMID 34242216, 2021). "RAB8A is one major subtype of RAB8 and is reported to be involved in female reproductive carcinogenesis such as cervical cancer and endometrial cancer, indicating its role as a potential gynecological tumor biomarker." (PMID 39856733, 2025). "Previous study confirmed RAB8A was up-regulated in endometrial carcinoma, which may be an effective tumor marker." (PMID 35435110, 2022). "Endometrial cancer tissue shows elevated expression of the Ras-related protein Rab-8A, as well as MST1 and PKN1, which could therefore serve as EC biomarkers." (PMID 27595026, 2016).
cervical cancer (3 papers, 2022 to 2025). A primary or metastatic malignant neoplasm involving the cervix. "Rab8A has been reported as an oncogenic gene in breast and cervical cancer." (PMID 36815135, 2023). "For example, Rab8A has been found to promote breast cancer progression by elevating surface expression of tropomyosin-related kinase B; Rab8A was reported to promote the growth and metastasis of cervical cancer." (PMID 36815135, 2023).
lung carcinoma (3 papers, 2020 to 2024). "This study reveals that except Rab7a, five Rab proteins, Rab8a, Rab11b, Rab27a, Rab35, and Rab37, were highly expressed in the purified AP of lung cancer cells (CL1‐5‐Q89L) with a high secretory tendency (Q) (column 4 vs. column 3)." (PMID 38804615, 2024).
colorectal cancer (2 papers, 2020 to 2023). A primary or metastatic malignant neoplasm that affects the colon or rectum. "Similarly, correlation-repressing genes RAB8A and LLGL2 associated with tight junction have previously been shown to be downregulated in colorectal cancer." (PMID 33384992, 2020).
cyst (2 papers, 2015 to 2020). A sac-like closed membranous structure that may be empty or contain fluid or amorphous material. "Wnt3a administration induced Rab8a+/+ organoids into a cyst-like morphology, an effect that was also observed for Rab8a-deficient organoids." (PMID 26015543, 2015). "Together, our results show similar functional requirements of Rab3A, Rab8A, Rab11A and Rab27A compared to what has been previously reported using MDCK cyst models of epithelial lumen formation." (PMID 32569321, 2020).
ovarian carcinoma (2 papers, 2024 to 2025). A malignant neoplasm originating from the surface ovarian epithelium. "In our study, we have identified a potential effector controlling RAB8A activity in ovarian cancer cells." (PMID 39856733, 2025). "Therefore, further study and develop the small-molecule antagonists targeting RAB8A could hopefully be a promising therapy of ovarian cancer." (PMID 39856733, 2025).
Atrophy (1 paper, 2014). Any weakening or degeneration, especially through lack of use. "Conversely, the localisation of Rab11a is altered in the intestinal epithelial cells of Rab8a knockout mice and in a microvillus atrophy patient, which has a mutation in the myosin Vb gene." (PMID 25527643, 2014). "Conversely, Rab11a is mislocalised in Rab8a knockout mice and in a microvillus atrophy patient, which has a mutation in the myosin Vb gene." (PMID 25527643, 2014).
autism spectrum disorder (1 paper, 2019). A spectrum of developmental disorders that includes autism, and Asperger syndrome. "The SYTL4 gene is known to directly interact with several members of the RAB family of genes, such as, RAB27A, RAB27B, RAB8A, and RAB3A which are known autism spectrum disorder genes." (PMID 31323913, 2019).
autoimmune thyroiditis (1 paper, 2025). "The study from 2023 showed that autoimmune thyroiditis is correlated to hypomethylation of Ras-related protein Rab-8A (RAB8A) and Ras-related protein Rap-1A (RAP1A), which corresponded to higher levels of mRNA expression." (PMID 39940256, 2025). "Patients with increased I exposure experience hypomethylation of most of the CpG locus of RAB8A, olfactory receptor family 4 subfamily K member 17 (OR4K17), and RAP1A, indicating that excess I is involved in the pathogenesis of autoimmune thyroiditis." (PMID 39940256, 2025).
cocaine addiction (1 paper, 2022). "Although no studies have shown that RAB8A has a direct effect on cocaine addiction, the biological process in which it participates is very important in cocaine addiction." (PMID 35493321, 2022).
diabetes (1 paper, 2020). "This is the first investigation with clear evidence that the OLE, as a potential insulin stimulator, can be used for the treatment of diabetes via the improvement of intracellular GLUT4 translocation in the skeletal muscle by the activation of Rab8A and Rab13 proteins." (PMID 33256066, 2020). "Since diabetes impairs both heavy and light chains of myosin, it seems that it has a negative effect on MyoVa and thus, Rab8A and GLUT4 vesicle movement." (PMID 33256066, 2020). "To test this hypothesis, we investigated the effect of olive leaf polyphenols (OLP) on Rab8A, Rab13, and Rab14, as well as GLUT4 in the soleus muscle of rats with streptozotocin-induced diabetes (SZT)." (PMID 33256066, 2020). "In addition, the significant correlation was detected between Rab13 and Rab14 (r = 0.8971, p = 0.000) in the groups with diabetes (diabetic control group and diabetic OLP-treated groups), while between Rab8A and Rab13, and Rab8A and Rab14, results were not significant." (PMID 33256066, 2020).
esophagus cancer (1 paper, 2023). "Knockdown of Rab8A suppressed the viability, colony formation, migration, and invasion abilities of esophagus cancer cells and induced apoptosis." (PMID 36815135, 2023). "The Wnt/β-catenin signaling pathway was positively regulated by Rab8A/PEA3 in esophagus cancer cells." (PMID 36815135, 2023). "In this study, we discovered that Rab8A was highly expressed in esophagus cancer samples, and knockdown of Rab8A suppressed the growth, migration, and invasion as well as induced apoptosis." (PMID 36815135, 2023). "PEA3 transcriptionally regulated Rab8A expression and promoted the viability, colony formation, migration, and invasion abilities of esophagus cancer cells and blocked apoptosis, which were diminished by si-Rab8A transfection." (PMID 36815135, 2023). "Additionally, the function of Rab8A depletion on esophagus cancer cells was reversed by PEA3 upregulation." (PMID 36815135, 2023). "A significant increase of Rab8A expression has been found in esophagus cancer cells." (PMID 36815135, 2023). "This study was performed to detect the function of Rab8A in esophagus cancer." (PMID 36815135, 2023). "In our study, PEA3 was identified as a transcriptional factor of Rab8A in esophagus cancer." (PMID 36815135, 2023). "Rab8A expression was detected by qPCR and western blotting assays, small interference RNA (siRNA) was applied to reduce Rab8A expression, and the biological behaviors of esophagus cancer cells were estimated by cell counting kit-8, colony formation, and transwell and western blotting assays." (PMID 36815135, 2023). "We described the transcriptional regulation of Rab8A in esophagus cancer." (PMID 36815135, 2023). "Additionally, more molecular mechanism about Rab8A in esophagus cancer should be revealed." (PMID 36815135, 2023). "The data showed that Rab8A was transcriptionally regulated by PEA3 and promoted the malignant behaviors of esophagus cancer cells by activating the Wnt/β-catenin pathway." (PMID 36815135, 2023). "The results showed that Rab8A and PEA3 were both highly expressed in esophageal cancer samples." (PMID 36815135, 2023). "Moreover, Rab8A was transcriptionally regulated by PEA3 and interacted with PEA3 to regulate the malignant behavior of esophagus cancer cells." (PMID 36815135, 2023). "Moreover, we also detected the protein expression of Rab8A and PEA3 in esophageal cancer tissues." (PMID 36815135, 2023). "However, the function and molecular mechanism of Rab8A in esophagus cancer has not been reported." (PMID 36815135, 2023). "However, the function and molecular mechanism of Rab8A in esophagus cancer has not been revealed." (PMID 36815135, 2023).
female reproductive cancers (1 paper, 2025). "As a multifunctional GTPase belonging to the Rabs family, RAB8A is involved in the development and metastasis of cancers including female reproductive cancers." (PMID 39856733, 2025).
hyperlipidemia (1 paper, 2020). "The deficiency of Rab8A in skeletal muscle was also linked with hyperlipidemia and hepatosteatosis in the organism due to impaired muscle lipid uptake and storage." (PMID 33256066, 2020).
Insulin resistance (1 paper, 2022). Increased resistance towards insulin, that is, diminished effectiveness of insulin in reducing blood glucose levels. "In conclusion, our results uncovered that statins inhibit GGPP production and induce insulin resistance in skeletal muscle cells through RhoA geranylgeranylation‐mediated insulin signalling‐dependent way and RAB8A geranylgeranylation‐mediated insulin signalling‐independent way." (PMID 35961942, 2022).
Niemann-Pick type C disease (1 paper, 2020). "The endolysosomal cholesterol and sphingolipid deposition in LSD fibroblasts from Niemann-Pick type C disease is rescued by overexpression of Rab8a, whilst depletion of Rab8a from wildtype fibroblasts causes an accumulation of endolysosomal cholesterol." (PMID 32581693, 2020).
prostate carcinoma (1 paper, 2025). A carcinoma that arises from epithelial cells of the prostate gland. "We grouped patients with prostate cancer in TCGA based on the expression of RAB8A." (PMID 39785769, 2025).
infection (18 papers, 2020 to 2025). The state of being infected such as from the introduction of a foreign agent such as serum, vaccine, antigenic substance or organism. "In the context of infection, Rab8A was observed to be recruited to the Salmonella invasion site, and SopD was shown to promote the upregulation and downregulation of pro- and anti-inflammatory cytokines, respectively." (PMID 38673776, 2024). "Consistent with the well-established defense roles of Rab8a against P. infestans, silencing Rab8a increased infection lesion sizes compared to the GUS-silencing control." (PMID 39365859, 2024). "Further research is required to determine the cargoes and the potential defense-related functions of Rab8a during infection." (PMID 34424198, 2021). "We detected a significant time‐dependent increase in Rab8A pT72 after infection with the pathogens confirming that infection triggers LRRK2 activation (Fig EV1A–C)." (PMID 32643832, 2020). "Taken together, these data suggest that trafficking of CD81 and p24 Gag to the cell periphery to form the TEM is compromised by knockdown of ARF1, BIN-1, RAB7L1, and RAB8A, potentially preventing the efficient trans-infection of virus via the VS." (PMID 32075937, 2020). "To finally test the oncogenic role of GPR137-RAB8A signal axis in OC progression in vivo, we established a SK-OV-3 cell line and an A2780 cell line that stably expressed GPR137-shRNA and RAB8A-shRNA by infection of levtiviruses carrying the shRNA sequences targeting GPR137 or RAB8A, respectively." (PMID 39856733, 2025). "Rab8A and Rab10 have yet to be studied in the context of SopD2 during infection." (PMID 38673776, 2024). "In future studies, it will be important to determine whether inhibition of Rab8A by SopD (and/or SopD221) impacts other pathways or stages of infection." (PMID 34349110, 2021). "To assess the effect of the Rab family on RSV replication, we depleted Rab1a, Rab2a, Rab4a, Rab5a, Rab6a, Rab7a, Rab8a, Rab9a, and Rab11a by treating A549 cells with specific siRNAs (or control siRNA) for 24 h, followed by infection with purified RSV A2 and incubation for another 36 h." (PMID 33504607, 2021). "ARF1, BIN1, RAB7L1, and RAB8A are required for HIV-1 trans-infection." (PMID 32075937, 2020). "Infection of macrophages with the M. tuberculosis ΔRD1 mutant, the yeast‐locked C. albicans Δhgc1 mutant or the L. monocytogenes Listeriolysin O Δhly mutant resulted in reduced levels of Rab8A pT72." (PMID 32643832, 2020). "These structures included ring shaped compartments that are reminiscent of PexRD54-autophagosomes as well as smaller densely packed GFP-positive puncta and large vacuole like structures, indicating that Rab8a could regulate diverse trafficking pathways during infection." (PMID 34424198, 2021). "We show that ADP-ribosylation factor 1 (ARF1), bridging integrator 1 (BIN1), and Rab GTPases RAB7L1 and RAB8A are important regulators of HIV-1 trafficking to the VS and therefore the infection of CD4+ T cells." (PMID 32075937, 2020). "However, pathogens infection significantly compromised the expression of mucin 2, ARHGAP17, RAB8A and MPP5." (PMID 38605016, 2024). "Therefore, it seems plausible that the depletion of RAB8A in MDDCs inhibits membrane recycling and therefore membrane protrusions, reducing HIV-1 trans-infection." (PMID 32075937, 2020). "Similarly in macrophages, pathogen infection induces lysosomal damage and was shown to result in relocalization of LRRK2 to the damaged lysosome where it phosphorylated Rab8A, and this recruited the ESCRT-III component CHMP4B that orchestrates the repair of lysosome damage." (PMID 38091401, 2023). "Conversely, in Rab8a-silenced plants, TOPGAP overexpression did not significantly alter infection lesion sizes compared to that in the EV control." (PMID 39365859, 2024).
tumor (13 papers, 2014 to 2025). "RAB proteins, including the RAB8A, have been determined to be associated with multiple cancers, and dysregulated interaction between RABs and their effectors could also link to tumor progression and malignancy." (PMID 39856733, 2025). "In this study, we have confirmed that the orphan receptor, GPR137, acts as a tumor promoter bolstering OC cell propagation through the RAB8A-mediated HH signaling activation." (PMID 39856733, 2025). "On the other hand, silencing of RAB8A led to a significant decrease in the proliferation of tumor cells but a significant elevation in the apoptotic OC cell rate, compared to that in the control tumors." (PMID 39856733, 2025). "The tumor-promoting effect of Rab8A has been involved in various physiological activities and signaling pathways." (PMID 36815135, 2023). "As DCs are the most potent antigen-presenting cells, we used this character to perform a comparative proteomic analysis of DCs and tumor lysate-pulsed DCs by LC-MS/MS, and found the expression of RAB8A to be significantly higher in HEC-DC and malignant endometrium tissues." (PMID 25477298, 2014).
cancer (7 papers, 2016 to 2025). A tumor composed of atypical neoplastic, often pleomorphic cells that invade other tissues. "Mechanistically, GPR137 enhances stabilization of RAB8A mRNA and the up-regulated RAB8A expression activates HH signaling by destroying the SuFu-GLI1 complex, leading to the release of GLI1 and thereby its translocation into the nucleus to trans-activates cancer-associated target genes." (PMID 39856733, 2025). "Additionally, the effect of Rab8A in cancer has been reported." (PMID 36815135, 2023). "However, there are few reports on the role of RAB8A in cancer progression." (PMID 35435110, 2022).
RAB8A also shares sentences with these, for which no sentence is quoted: retinal degeneration (6 papers); hepatocellular carcinoma (3); Joubert syndrome (3); Bardet-Biedl syndrome (2); breast carcinoma (2); memory impairment (2); microvillus inclusion disease (2); oculocerebrorenal syndrome (2); pancreatic cancer (2); autism (1); autosomal recessive deafness (1); bacterial infection (1); bladder cancer (1); chlamydial infections (1); Cholestatic liver disease (1); colon adenocarcinoma (1); dementia (1); enteritis (1); epidermoid carcinoma (1); gastric cancer (1); gestational diabetes mellitus (1); glaucoma (1); gynecological tumor (1); Hyperglycemia (1); lateral sclerosis (1); Leber congenital amaurosis (1); leukopenia (1); liver disease (1); lung adenocarcinoma (1); lung squamous cell carcinoma (1).
A further 10 diseases each share a sentence with RAB8A in 1 paper.